CACNA1C (calcium voltage-gated channel subunit alpha1 C)
Diseases named in the same sentence as CACNA1C in open-access papers (continued):
Sharing a sentence is not in itself a finding about the gene and the disease.
cardiovascular diseases (13 papers, 2010 to 2025). "Due to its pivotal role in neurons and cardiac myocytes, CACNA1C has emerged as a major target of interest in neuropsychiatric and cardiovascular disease." (PMID 37372947, 2023). "Haploinsufficient Cacna1c+/− rats represent a recently developed animal model for studying the role of Cav1.2 in psychiatric and cardiovascular disease." (PMID 37372947, 2023). "Previous studies showed that alternative splicing, proteasomal ubiquitination degradation, and oxidative stress could regulate CACNA1C expression, which was involved in the pathogenesis of some cardiovascular disease." (PMID 35711357, 2022). "Understanding the splicing patterns of CACNA1C in diseases may not only help us evaluate the functional changes of CaV1.2 channels, but also provide potential therapeutic targets for developing novel methods to manage cardiovascular diseases." (PMID 29186814, 2017).
neurological disorders (10 papers, 2010 to 2025). "CACNA1C variants have also been found in patients who present with neurological disorders alone, including developmental delay, epilepsy, and intellectual disability." (PMID 41274879, 2025). "Genetic variants in CACNA1C are associated with both cardiac and neurological disease." (PMID 41274879, 2025). "Their important role in brain is underscored by studies showing genetic variation in the CACNA1C gene encoding Cav1.2, the major voltage-sensing and pore forming α1 subunit expressed in brain, is associated with neurodevelopmental, psychiatric and neurological disorders." (PMID 31663850, 2019).
infection (6 papers, 2019 to 2025). The state of being infected such as from the introduction of a foreign agent such as serum, vaccine, antigenic substance or organism. "This suggests that respiratory concerns and infection are common and potentially life-threatening among individuals harboring a CACNA1C variant." (PMID 39580446, 2024). "While no Gly402Ser individuals had immunological concerns, those with other variants in CACNA1C reported frequent infections, including 9/11 (82%) respondents diagnosed with nsLQT8 and 11/21 (51%) of those within the other variant category." (PMID 39580446, 2024). "In HEK293T-ACE2/TMPRSS2 cells, the viral RNA level in CACNA1C-silenced cells was lower than that in siControl-transfected cells at 6 h post-infection." (PMID 35176124, 2022).
neurodegenerative disease (5 papers, 2016 to 2021). A disorder of the central nervous system characterized by gradual and progressive loss of neural tissue and neurologic function. "CACNA1C is a voltage-dependent calcium channel and has been previously linked to several neurodegenerative diseases." (PMID 27115429, 2016).
adenocarcinoma (2 papers, 2015 to 2023). A common cancer characterized by the presence of malignant glandular cells. "Expression of CACNA1C is indirectly affected by the hemimethylated of CACNA1C-AS1 CPG codon, which is considered the master gene of intestinal-type adenocarcinomas." (PMID 37183262, 2023).
brain diseases (2 papers, 2018 to 2020). "CACNA1C (rs1024582) and CACNB2 (rs2799573) polymorphisms were suggested as the common risks across seven brain diseases." (PMID 33338084, 2020).
skin disorder (1 paper, 2024). Any deviation from the normal structure or function of the skin or subcutaneous tissue that is manifested by a characteristic set of symptoms and signs. "Skin disorders were noted among individuals with CACNA1C variants across the different groups." (PMID 39580446, 2024).
vascular disorder (1 paper, 2022). A general term used to describe any disease affecting blood vessels]. "In light of the important roles of CACNA1C in the occurrence and progression of vascular disorders, monitoring the CACNA1C promotor methylation may have a significant clinical value for the prediction of some vascular diseases." (PMID 35711357, 2022).
CACNA1C also shares sentences with these, for which no sentence is quoted: cardiac arrhythmias (27 papers); genetic disorder (8); Obesity (5); catecholaminergic polymorphic ventricular tachycardia (4); myocardial infarction (4); bladder cancer (3); cerebellar ataxia (3); early repolarization syndrome (3); Hyperglycemia (3); idiopathic ventricular fibrillation (3); ischemia (3); melanoma (3); osteoporosis (3); Sinus bradycardia (3); Andersen syndrome (2); Angelman syndrome (2); anxiety disorder (2); aortic stenosis (2); asthma (2); atrial tachycardia (2); cognitive disorder (2); colon cancer (2); deafness (2); diabetic cardiomyopathy (2); dyslipidemia (2); endometrial cancer (2); endothelial dysfunction (2); epileptic encephalopathies (2); Hodgkins lymphoma (2); Hypercholesterolemia (2).
A further 125 diseases each share a sentence with CACNA1C in 2 papers or fewer.